KIT (KIT proto-oncogene, receptor tyrosine kinase)
Diseases named in the same sentence as KIT in open-access papers (continued):
Sharing a sentence is not in itself a finding about the gene and the disease.
cancer (continued). "Among others, we also identify a proto-oncogene gene KIT (also known as CD117), which has a critical role in various cancer-related cellular processes, including cell survival, proliferation, and differentiation across multiple distinct cancers." (PMID 41358317, 2025). "Using the OncoGuide NCC Oncopanel System (114 genes) and FoundationOne CDx Cancer Genomic Profile (324 genes), they identified alterations in KIT (78%), PDGFRA (6%), and SDHB (6%)." (PMID 41355515, 2025). "This approach identified signals that are known to be critical for cancer growth, such as KIT–KITL and CD47–thrombospondin 116, as well as multiple new signalling axes." (PMID 40369079, 2025). "Dysregulated KIT function promotes tumourigenesis and progression various cancer types through its activation or inappropriate expression." (PMID 38787171, 2024). "Aberrant expression of KIT in some HCC patients is associated with specific HCC subtypes, impacting cancer invasiveness and prognosis." (PMID 39399471, 2024). "These are alterations in the BRAF gene, alterations in the KIT gene, rearrangements of the antigen receptor genes, and alterations in panels of known cancer genes." (PMID 38787171, 2024). "The MYC, KIT and KRAS genes, all of which are implicated in various cancers, comprise G4-forming sequences within their promoters." (PMID 38407356, 2024). "Downstream activation caused by this gene fusion targets many “blockbuster” genes such as PDGF, VEGF, FGFR, or KIT known to be deregulated in many cancer types." (PMID 39411551, 2024). "The development of imatinib, a small molecule that inhibits the activity of the KIT tyrosine kinase, has brought about a remarkable paradigm shift in the clinical management of cancer patients." (PMID 39516322, 2024). "We have demonstrated by IHC screening that HER2, EGFR1, VEGFR-2, PDGFR-β and ERK1/ERK2 are commonly overexpressed in dogs with different carcinomas, and KIT expression is considered relatively low in the analyzed samples." (PMID 39126006, 2024). "KIT codes for the receptor tyrosine kinase c-KIT, often upregulated in various cancers, leading to enhanced cell survival and proliferation." (PMID 36817445, 2023). "Mutations in exon 11 of the KIT gene were detected in 28 of 48 (58.3%) GIST patients and predicted to be pathogenic and cancer promoting." (PMID 37574490, 2023). "The hit compound displayed high selectivity against KIT autophosphorylation at Y703 in a GIST430 cancer cell line over 28 kinases." (PMID 37298401, 2023). "The KIT gene was our chosen target because of its significance in cancers such as AML and its critical functions in hematopoiesis." (PMID 37513844, 2023). "ADC NN2102-DM1 was observed to be efficient in KIT-expressing cancer in mouse models, which offers another promising way of targeting both mutant and wild-type KIT." (PMID 38313431, 2023). "BCL2 and KIT, i.e., oncogenes/proteins commonly overexpressed in tuft cell-like carcinomas, were expressed in one of the two triple-negative cases." (PMID 37179317, 2023). "Alternatively, the oncogene KIT, described for its role in PTC and other cancers, encodes a receptor tyrosine kinase that affects cellular growth and differentiation." (PMID 35681658, 2022). "Activation of c-KIT is observed in various cancers including GIST, mast cell tumors, and malignant melanomas." (PMID 36612139, 2022). "Another study assessed therapy with imatinib and NN2101-DM1, a conjugated IgG1 and microtubule inhibitor, both together and alone in c-KIT mutant cancers in mouse models." (PMID 35954441, 2022).
cancer (continued). "These drug molecules target adenosine receptor (A2AR), vascular endothelial growth factor receptor (VEGFR), platelet-derived growth factor receptor (PDGFR), and type III stem cell receptor tyrosine kinase (c-KIT), which plays a crucial role in cancers." (PMID 36052261, 2022). "In mutant-KIT-driven cancers, mutant KIT is auto-phosphorylated and this autophosphorylation process is independent of SCF stimulation." (PMID 35999600, 2022). "Treatment success of KIT-induced cancers is still unsatisfactory because of primary or secondary resistance to therapy." (PMID 36396684, 2022). "Truncating variants were also detected in two lesser-known cancer susceptibility genes, namely PTCH1 (NM_000264.5):c.4187delG, p.Gly1396AspfsTer56 and KIT (NM_000222.3):c.930delA, p.Gly311AspfsTer8." (PMID 36568162, 2022). "In NB tumors and cell lines, KIT-positive cells constitute a sub-population of stem-like cancer cells, and KIT-positive NB cells generate more aggressive tumors than KIT-negative cells." (PMID 35887076, 2022). "Studies on non-small lung cancer have also related c-KIT to cancer stemness, based on findings that revealed a reduction of CSCs through targeting the SCF-c-KIT autocrine signaling loop and inhibition of c-kit with specific shRNA and inhibitors." (PMID 35490363, 2022). "In many cancers, such as GIST, mast cytosis, and AML, the activation of KIT was detected through overexpression or mutation." (PMID 35563085, 2022). "Changes in c-KIT can thus play a role in various types of cancer, influencing metastasis, tumor growth, and cell proliferation." (PMID 35954441, 2022). "GCNIS-like cells with big, vacuolated cytoplasm and increased expression of OCT-4, SSEA-1, SCA-1 and CD166 (cancer stem cells marker) along with reduced c-KIT, MVH and PTEN were evident." (PMID 35676718, 2022). "Next, we analyzed the gene dependency data from the Cancer Dependecy Map (DepMap) for KIT depletion by RNAi." (PMID 35887076, 2022). "This novel disease model is expected to facilitate future studies addressing the identification of genetic and environmental factors affecting disease progression in KIT-induced cancer." (PMID 36396684, 2022). "After 2 and 4 h incubations of cancer MDA-MB-231 cells with FAM labeled siRNA as reporter molecule loaded in [FA-PEGylated/PEI@GuIL@KIT-6], the cells were collected, harvested and prepared for flow cytometry analysis." (PMID 36241668, 2022). "The refinement of these highly selective therapeutic tools, either alone or combined with chemotherapeutic agents, TK inhibitors, or immune checkpoint inhibitors, will help treat cancer types driven by the c-KIT signaling machinery." (PMID 35490363, 2022). "Cenisertib inhibits the kinase activity of AKT as well as FLT3, VEGFR2, LYN, BTK, and KIT and promotes growth inhibition, cell cycle arrest, and apoptosis in many cancer cell lines." (PMID 36590916, 2022). "It was found that 6r remarkably attenuates proliferation of cancer cells via blockade of c-KIT downstream signaling, and induction of apoptosis and cell cycle arrest." (PMID 36612139, 2022). "It was reported that hyper-methylation in the promoter region of c-KIT proto-oncogene would result in the down-regulation of gene expression in most cancer tissues." (PMID 36062142, 2022). "Immunohistochemistry for human Nucleoli, pan-cytokeratin and KIT confirmed the presence of KIT-expressing invasive stroma-rich carcinomas initiated by PDO2KIT." (PMID 35842424, 2022). "It was also observed that strong expression of c-KIT was found in 50% of malignant tumors and 5% of benign tumors." (PMID 34123614, 2021). "The mRNA expression of KRAS, BRAF, and KIT in various types of cancer from TCGA samples were analyzed using the UALCAN database (Figure A1 and Figure A2 in Appendix A)." (PMID 34769348, 2021). "These types of childhood cancers share common features including the aberrant expression of receptor tyrosine kinases (RTK) such as KIT and NTRK1." (PMID 34944663, 2021).
cancer (continued). "Although the role of BRAF, KRAS, and KIT in transcriptomic alterations, tumorigenesis, and progression of several cancers has been partially elucidated, bioinformatics analysis in SKMs has yet to be confirmed." (PMID 34769348, 2021). "KIT is a well-known oncogene, and its inhibition shows promising results for the treatment of several cancers." (PMID 34572789, 2021). "Increased c-KIT (CD117 expression) in PTs showed positive rate in 29% benign, 17% borderline and 24% frank malignant tumors." (PMID 34123614, 2021). "Recurrent alterations at the same genomic site in cancer genes such as MET, MPL, FLT3, and KIT have been implicated in many different cancer types." (PMID 34068918, 2021). "HotPho successfully identifies likely functional mutational clusters and phosphosites in known cancer proteins, including EGFR, KIT, and KRAS/HRAS/NRAS, many of which are in kinase domains." (PMID 33875650, 2021). "On the other hand, the commonly downregulated included Pyruvate Dehydrogenase Kinase 4 (PDK4) in 15 cancers and KIT proto-oncogene receptor tyrosine kinase (KIT) in 13 cancers, among the cancers analyzed." (PMID 33801837, 2021). "In contrast the expression of MT1X, MT2A, IL10RA, KIT was lower in cancer tissues as compared to normal tissues." (PMID 33240582, 2020). "Compared with CD83-OV and control groups, CD83-KD cancer cells showed a reduction of stemness factors, including KIT, CD44, and SOX2." (PMID 32823589, 2020). "We communicate the first structural model of the full-length RTK KIT cytoplasmic domain, a crucial target for cancer therapy." (PMID 32214210, 2020). "Imatinib inhibits kinase activities of c-ABL, BCR-ABL, c-KIT, and PDGFRβ activity suppressing the proliferation of cancer cells." (PMID 32756477, 2020). "In previous works, we identified two promising G4 ligands (AQ1 and AN6) that reduced KIT expression in cancer cells by a direct recognition of its promoter." (PMID 33396937, 2020). "Unlike that the important role of PI3 kinase relies on its lipid kinase activity in cancers, we previously found that the key role of PI3 kinase in KIT mutation mediated cell transformation is independent on the lipid kinase activity of PI3 kinase." (PMID 32082541, 2020). "Specifically, poorer survival was associated with samples that had a SPRED1 aberration in combination with another cancer driver mutation: NRAS, NF1 or KIT (log-rank test, p = 0.0074)." (PMID 33067454, 2020). "To evaluate if these effects were seen in other cancer types, we also treated KIT-mutant GIST cells with imatinib." (PMID 31727958, 2019). "Novel compounds have shown promising data on IM-refractory GISTs in the early phases of clinical trials; however, new drug development in advanced GISTs still mainly targets the KIT inhibition despite the emergence of immunotherapy in other types of cancers." (PMID 31607749, 2019). "We also report that SLC18A2, PLXNC1, and MRPL33 gene expression is associated with TrkA or KIT expression levels in both AML and NB, and these genes have a prognostic value for both cancers." (PMID 31681584, 2019). "We also investigated four genes, RAI2, KCNMA1, NBEA, and KIT, in the two ranking lists, and their potential functions for these two types of cancer." (PMID 31888440, 2019). "In certain types of cancers, such as gastrointestinal stromal tumors or mastocytosis, KIT is the major target for therapy, primarily by imatinib." (PMID 30931942, 2019). "Certain human cancers, including CML, are characterized by aberrant KIT tyrosine kinase activity, and KIT is implicated in CML pathogenesis." (PMID 30825668, 2019).
cancer (continued). "KIT is a major pro-survival receptor for certain types of cells, and thus its inhibitors are used in cancer therapy." (PMID 30931942, 2019). "We further analyzed pathways of the predicted five cancer driver genes and found that KIT, ERBB2 and CEBPA are related to PI3K and RAS pathways." (PMID 32039169, 2019). "Recent studies have shown that KIT can promote the proliferation and invasion of cancer cells through activating Akt and extracellular regulated protein kinase 1 (ERK1)/2 pathways." (PMID 30825668, 2019). "The proto-oncogene KIT encodes a receptor tyrosine kinase that plays an important role in many cellular processes including hematopoiesis, and therapeutic targeting of KIT signaling in cancer is an area of intense research." (PMID 30470245, 2018). "In line with previous observations, genes involved in cancer development were represented on Bs of four studied species: red fox (KIT), Chinese raccoon dog (ENPP1, GNAS, HMGCR, KDR, RET), brocket deer (BCL6, RASA1, RET), and Korean field mouse (JAK3)." (PMID 30103445, 2018). "Recently, we demonstrated that an anthraquinone derivative (named AQ1) significantly downregulated KIT mRNA and protein levels in several human cancer cell lines, thereby preventing their proliferation." (PMID 30459395, 2018). "Several genes account for a large proportion of variant/drug interactions (e.g., EGFR, KIT, ERBB2, BRCA1, PDGFRA), reflecting interest in therapeutically exploiting a relatively limited number of cancer driver genes." (PMID 30053901, 2018). "In concordance with this, the KIT D816V mutant also shared the same inhibitor against cancer with HCK and LYN30." (PMID 29844492, 2018). "KIT is also a member of the cancer driver gene panel whose transcription is downregulated by P-bi-TAT." (PMID 30135398, 2018). "Upon co-culture of cancer-derived exosomes with a human uterine leiomyomatous smooth-muscle cell line, exosomes were taken up and cytosolic and membranous KIT expression was detected in 100% of observed cells within 24 h." (PMID 28796150, 2017). "In this study, oncogenic protein tyrosine kinase (KIT) was found to be packaged in cancer-derived exosomes." (PMID 28796150, 2017). "In xenografts models of human PC with low c-KIT expression, the receptor is upregulated during cancer progression through production of stem cell factor in the bone microenvironment." (PMID 29207991, 2017). "Cell proliferation rate is an important prognostic factor of malignant tumors, and it can be regulated by KIT/MAPK/MEK signaling pathway." (PMID 29137292, 2017). "It suggested that the important role of KIT as an oncogene in the progression of cancer, as well as a tyrosine-protein kinase during the normal activity." (PMID 29050270, 2017). "Two carcinomas each harbored a missense mutation in the fibroblast growth factor receptor 3 (FGFR3) and the receptor tyrosine kinase KIT." (PMID 27844328, 2017). "Some of the significantly mutated indel regions occur within genes with a well-established connection with cancer development, such as KIT, BRAF or PTEN." (PMID 27150584, 2016). "Next, we analyzed 274 mutations in 24 cancer-relevant genes (Sequenom technology), including BRAF, NRAS, KIT c-MET, GNAS and GNAQ." (PMID 27057633, 2016). "In contrast, we observed a KIT+CD11b+ population present only in the peripheral blood of cancer patients and whose frequency decreased significantly under therapy with paclitaxel and bevacizumab compared to paclitaxel only." (PMID 26840567, 2016). "The analysis revealed that MAPK12, RAPGEF3, and KIT exhibited the most betweenness centrality and all were related to the cancer progression." (PMID 28044124, 2016).
cancer (continued). "Targeting KIT or other tyrosine kinase receptors has been at the epicenter of this exponential genomic research, and has opened new avenues in cancer classification and management." (PMID 27509178, 2016). "Mutations in cis-acting splicing elements were shown in both oncogenes (KIT, CDH17, and BRCA1/2) and tumor suppressors (LKB1 and KLF6), which have causal role in cancer initiation and progression." (PMID 28105922, 2016). "The only rare variant detected in all three experiments using 314 and 318 chips is located in the “hotspot” regions of cancer-related gene KIT." (PMID 26709353, 2016). "qRT-PCR was performed to verify GEP findings and analyze the relationship between copy number change and expression change in four well known cancer associated genes including MYC, KIT, FLT3, and PTEN." (PMID 27639374, 2016). "The c-KIT gene codes for the KIT tyrosine kinase gene product, which is implicated in a number of human cancers, notably gastro-intestinal cancer (GIST), where dis-regulation of c-KIT expression is the primary causative event of this disease." (PMID 25452341, 2015). "Particularly growth factor receptors, such as HER2, EGFR, VEGFR or c-KIT, which are strongly up regulated in many cancers, have proven to represent efficient anti-cancer therapy targets." (PMID 26555375, 2015). "Overall, this study identifies SHP2 as a therapeutic target in aggressive SM which frequently harbor activating KIT mutations, and also provides further support for combining SHP2 and tyrosine kinase inhibitors in other relevant cancer models." (PMID 25026279, 2014). "There is a sharp difference in c-KIT mRNA levels between the steady states of Rc on the lower and upper branches in the steady-state bifurcation diagram, which would suggest cancer phenotype-promoting over-expression of c-KIT mRNA for k5>k5R." (PMID 25545504, 2014). "SHP2 KD cells showed reduced phosphorylation of ERK compared to NT control cells, and this is consistent with SHP2 silencing in other KIT-driven cancer models." (PMID 25026279, 2014). "Other important tyrosine-protein kinase family in PHYMA includes the proto-oncogene KIT that has been shown to be involved in cancer progression, via promoting cellular survival and proliferation." (PMID 24626295, 2014). "Imatinib, a potent CD117 (c-KIT) specific inhibitor, has been used in clinical trials for the treatment of many types of cancer, including persistent epithelial ovarian cancer." (PMID 23902592, 2013). "This event resulted in a marked increase in KIT expression levels when the molecule was administered to human cancer cells." (PMID 24108400, 2013). "The RAS, RAF, PIK3CA, AKT,ERBB1, KIT, FMS and ETS oncogenes are also contained as viral oncogenes in the genomes of certain retroviruses that cause cancer in animals." (PMID 21422497, 2011). "This combination is interesting because it simultaneously inhibits two different molecules of the same signaling pathway (KIT-PDGFRA/PI3-K/AKT/mTOR) that impacts on cancer cell growth, survival, motility and metabolism." (PMID 21192792, 2010). "This high level of overexpression of KIT in GISTs probably reflects the selection pressure favoring the expression of this gene during clonal cancer evolution." (PMID 18803840, 2008). "For example, the fact that by far the highest levels of KIT expression across all samples available were seen in GISTs demonstrates that one could identify key driver genes that are mutated or otherwise activated in human cancers and could, therefore, be of significant therapeutic significance." (PMID 18803840, 2008).